EGFR (epidermal growth factor receptor)
Diseases named in the same sentence as EGFR in open-access papers (continued):
Sharing a sentence is not in itself a finding about the gene and the disease.
lung adenocarcinoma (continued). "The migration and invasion potential in lung adenocarcinoma cells is promoted by a few MMP proteins, for example MMP1 has been associated to migration and invasion in lung adenocarcinoma resistant to epidermal growth factor receptor tyrosine kinase inhibitors (EGFR-TKI)." (PMID 34356991, 2021). "Between May 2010 and December 2018, we investigated 363 patients with advanced lung adenocarcinoma harboring EGFR mutations who received EGFR TKIs." (PMID 33430803, 2021). "Lung adenocarcinomas with activating mutations in the epidermal growth factor receptor (EGFR) gene represent the most common subset of targetable driver-positive non-small cell lung cancers (NSCLCs) and comprise ~10–15% of Caucasian patients and ~40–50% of East-Asian advanced NSCLC patients." (PMID 34572868, 2021). "In addition, our previous experiments using the HCC827 lung adenocarcinoma cell line (carrying the EGFR exon 19 deletion mutation, del E746_A750) indicate that cancer cells are flexible enough to always find a way to survive." (PMID 34202566, 2021). "Therefore, osimertinib is currently the first therapeutic choice for EGFR mutation‐positive lung adenocarcinoma." (PMID 33586356, 2021). "The results of our present study can contribute to the development of effective therapeutic strategies for osimertinib in EGFR mutation-positive lung adenocarcinoma cases by focusing on the characteristics of EphB4 as a predictor of the therapeutic effects of osimertinib and as a prognostic factor." (PMID 34445227, 2021). "The aim of the current study is to investigate potential associations among Long Noncoding RNA (LncRNA) H19 single nucleotide polymorphism (SNP) and epidermal growth factor receptor (EGFR) phenotypes on the clinicopathological characteristics of lung adenocarcinoma (LADC)." (PMID 33799753, 2021). "Lung adenocarcinoma (LUAD) harboring EGFR mutations prevails in Asian population." (PMID 33144684, 2021). "Only a few antihypertensive drugs have been evaluated with favorable results in clinical trials, as noted in this review, and just one of them in phase III, which was the combination of a β-blocker with afatinib in patients with lung adenocarcinoma and EGFR mutations." (PMID 34094953, 2021). "The existence of at least one G genotype (CG and GG) allele on WWOX rs3764340 exhibited a significant association with the involvement of nearby lymph nodes in the lung adenocarcinoma patients harboring EGFR mutations, particularly those with the EGFR L858R mutation." (PMID 34948746, 2021). "Somatic activating mutations in the tyrosine kinase domain of the EGFR gene are observed in 15% of patients with lung adenocarcinoma, and more frequently in those with lepidic and acinar subtypes, with exon 19 deletion (62%) and L858R point mutation in exon 21 (38%) being the most common." (PMID 33922215, 2021). "After pivotal trials proved strong activity of gefitinib in patients with EGFR mutation-positive (del19, L858R) lung adenocarcinoma, subsequent phase II trials demonstrated the efficacy of gefitinib in the upfront treatment setting with an ORR of 55% to 75% and a median PFS of 9.2 to 9.7 months." (PMID 33671873, 2021). "Our data suggest-that examining WWOX SNPs, rs3764340 and rs73569323, may help identify patients with lung adenocarcinoma with EGFR L858R mutations that have a higher risk of tumor size (T) and affected lymph node (N) status." (PMID 34948746, 2021). "Loss of LATS1/2 or other Hippo pathway alterations could confer resistance to erlotinib in HNSCC cells with EGFR overexpression or lung adenocarcinoma cells harboring EGFR mutations." (PMID 34725466, 2021). "Thus, after the publication of the new classification of lung adenocarcinoma, several studies attempted to identify the relationship between EGFR mutation and histological subtypes." (PMID 34026636, 2021).
lung adenocarcinoma (continued). "Another small retrospective study studied the effects of bisphosphonates in patients with EGFR-mutated lung adenocarcinoma and bone metastases (n = 62) and found comparable results (PFS and OS prolonged in the bisphosphonate + EGFR-TKI group compared with the EGFR-TKI group)." (PMID 34201833, 2021). "Interestingly, Axl is more frequently overexpressed in lung adenocarcinomas that display EGFR-activating mutations, when compared to those that have wild-type EGFR." (PMID 33806258, 2021). "Therefore, osimertinib is becoming the gold standard for the treatment of patients with EGFR mutation-positive lung adenocarcinoma, and its use is expected to expand in near future." (PMID 34445227, 2021). "In this study, we evaluated whether tissue Romo1 expression was associated with clinical outcomes in epidermal growth factor receptor (EGFR)-mutated lung adenocarcinoma treated with tyrosine kinase inhibitors (TKIs)." (PMID 34956890, 2021). "We found that the lung adenocarcinoma patients with both EGFR mutation and WWOX rs3764340 C/G polymorphism may be prone to the involvement of nearby lymph nodes, especially those with EGFR L858R mutation." (PMID 34948746, 2021). "The data demonstrated that lung adenocarcinoma patients with EGFR L858R mutation, accompanied by WWOX rs73569323 C > T polymorphism, may show large tumor size and invasion of adjacent tissues." (PMID 34948746, 2021). "Hence, we evaluated the use of polycaprolactone electrospun (PCL-ES) scaffolds for culturing LCSC population in sensitive and resistant EGFR-mutated lung adenocarcinoma models." (PMID 34771484, 2021). "Besides, radiomics signatures extracted from ADC, DWI, T2WI can be used for predicting EGFR mutation in patients with lung adenocarcinoma." (PMID 34663307, 2021). "Therefore, using the TCGA database, we analyzed the mRNA expression of each of these chemokines in lung adenocarcinoma (LUAD) patients with EGFR oncogenic mutations and compared these gene expression profiles to tumours with wt EGFR." (PMID 35052732, 2021). "Lung adenocarcinomas display mutations in several genes, especially K-Ras and EGFR." (PMID 34359807, 2021). "Uncommon EGFR mutations such as exon 18 (E709X and G719X), exon 19 (exon 19 insertions), exon 20 (exon 20 insertions and S768I), and exon 21 (L861Q) mutations constitute the remaining 10–15% of EGFR-mutated lung adenocarcinomas, which display variable sensitivities to EGFR TKIs." (PMID 34572868, 2021). "For example, epidermal growth factor receptor inhibitors are a cornerstone in the treatment of patients with advanced lung adenocarcinoma who harbor epidermal growth factor receptor mutations but may prolong the QT interval." (PMID 34913360, 2021). "Our study suggests that radiotherapy combined with gefitinib could improve the survival of patients with locally advanced EGFR-activating mutation lung adenocarcinoma." (PMID 32563259, 2020). "Both the causal networks of osimertinib intervention and MNK1/2 identified significantly and differentially, respectively, may evidence disease mechanisms associated with EGFR mutation-positive lung adenocarcinoma." (PMID 32983988, 2020). "However, this is hard to generalize because the number of KRAS mutated lung adenocarcinoma is much smaller (n = 6) than EGFR mutated adenocarcinoma (n = 15) in this study cohort." (PMID 32196518, 2020). "Most of the recruited patients with lung adenocarcinoma in the present study had EGFR mutation." (PMID 32344833, 2020). "EGFR mutations were detected in 58 (48.7%) of 119 patients with advanced lung adenocarcinoma." (PMID 32093452, 2020). "Therefore, EGFR-TKIs are used as a standard first-line therapy for advanced lung adenocarcinoma patients with sensitive EGFR mutations (L858R or exon 19 deletion)." (PMID 32092879, 2020).
lung adenocarcinoma (continued). "Development and validation of a radiomics nomogram based on PET/CT radiomic features combined with clinicopathological factors may guide targeted therapy for patients with lung adenocarcinoma with EGFR mutations." (PMID 33262942, 2020). "Furthermore, the CA9 SNP rs2071676 is correlated to lower tumor stage and lower risk for developing lymph node metastasis in lung adenocarcinoma, mainly in the EGFR wild type." (PMID 32365566, 2020). "We performed the same analysis separately in lung adenocarcinoma patients with EGFR mutation." (PMID 32552717, 2020). "In addition, the potential effects of different forms of CA9 SNP and EGFR mutations on the severity of lung adenocarcinoma were also evaluated." (PMID 32365566, 2020). "Moreover, in a prospective clinical trial of stage IV lung adenocarcinoma with mutated EGFR, the addition of bevacizumab to the standard tyrosine kinase inhibitor (TKI) treatment increased progression free survival and reduced BM formation." (PMID 32918638, 2020). "In conclusion, our study determined that there was more apoptosis in EGFR‐mutant lung adenocarcinoma patients, and exosomes of EGFR mutation cell lines could promote CD8 + T cell apoptosis." (PMID 32500560, 2020). "Clinically, afatinib could be an effective treatment for lung adenocarcinoma patients with the EGFR mutation and brain metastasis." (PMID 33489886, 2020). "In conclusion, in our study of patients with stage IIIb or IV lung adenocarcinoma with EGFR mutations who received TKIs as the first-line treatment, a lower lymphocyte percentage, and higher platelet counts were significantly associated with shorter PFS and OS." (PMID 32702917, 2020). "On the other hand, genetic studies involving multi-region sequencing of tumors have clearly shown that genetic heterogeneity exists in lung adenocarcinoma and EGFR mutations generally occur in the genetic trunk of the tumor and are hence clonal, whereas KRAS mutations are often sub-clonal." (PMID 33520716, 2020). "Furthermore, our results strengthen the requirement for a combinative blockade in lung adenocarcinoma harboring EGFR Del E746-A750 mutation." (PMID 33426073, 2020). "This study analysed the clinical significance of EGFR mutation types in lung adenocarcinoma." (PMID 32053675, 2020). "In the present study, we report the cases of two synchronous lung adenocarcinomas, composed of two distinct pathological subtypes harboring epidermal growth factor receptor (EGFR) gene mutation and echinoderm microtubule-associated protein-like 4-anaplastic lymphoma kinase (EML4–ALK) rearrangement." (PMID 32727606, 2020). "HCC827 are lung adenocarcinoma cells that have acquired mutation in an EGFR tyrosine kinase domain." (PMID 32161259, 2020). "Between May 2014 and December 2016, a total of 4,889 advanced lung adenocarcinoma patients with the EGFR mutation receiving TKIs (including 1,778 gefitinib, 1,599 erlotinib, and 1,512 afatinib) as first-line therapy were included in our study." (PMID 33489886, 2020). "Furthermore, according to the PIONEER study, up to 51% of all newly diagnosed untreated Stage IIIB/IV lung adenocarcinoma in Asia harbor an EGFR mutation." (PMID 32523650, 2020). "Somatic mutations in the epidermal growth factor receptor (EGFR) leading to aberrant autophosphorylation of its cytosolic domain tyrosine residues and subsequent activation of survival and proliferation signal pathways are observed in lung adenocarcinoma." (PMID 33096790, 2020). "Interestingly, a recently completed clinical trial reported increased efficacy of autologous NK cell transfer in patients with epidermal growth factor receptor (EGFR)-mutated advanced lung adenocarcinoma compared to EGFR wild-type." (PMID 32751977, 2020). "Moreover, AG + GG polymorphic genotypes of SOD rs4880 are significant correlated with advancer cancer stage and distant metastasis in EGFR-mutated lung adenocarcinoma patients." (PMID 32937815, 2020).
lung adenocarcinoma (continued). "The L858R expression is a common type of EGFR mutation in lung adenocarcinoma, which related to a longer overall survival and lower tumor mutation burden value compared to EGFR wild type, but the prognosis of a L858R mutation is worse than the deletions in exon 19 phenotype." (PMID 32365566, 2020). "Our proposed scoring model may enable tailored treatment approaches in patients with EGFR-mutated lung adenocarcinoma treated with standard TKI." (PMID 33370365, 2020). "Therefore, we examined the association between the FGFR4 SNPs and EGFR mutation in Taiwanese patients with lung adenocarcinoma." (PMID 32781755, 2020). "In conclusion, the data suggest that FGFR4 SNPs may help in identifying patient subgroups at low-risk for tumor metastasis, among carriers of lung adenocarcinoma bearing wild-type EGFR." (PMID 32781755, 2020). "Clinically relevant GSI, nirogacestat, showed similar activity in combination with gefitinib in an EGFR T790M lung adenocarcinoma cell line xenograft model, providing further rationale for this combined therapeutic strategy in patients with EGFR “gate-keeper” mutations." (PMID 32575680, 2020). "Large-scale, population-based real-world studies on the treatment outcomes of first-line tyrosine kinase inhibitors (TKIs) and subsequent systemic chemotherapy agents for lung adenocarcinoma (with activating epidermal growth factor receptor [EGFR] mutations) remain limited." (PMID 33489886, 2020). "The data indicated that the CD44 rs11821102 G/A polymorphism might influence unique microRNA, thereby altering specific CD44 mRNA subtypes in male patients with lung adenocarcinoma harboring the EGFR L858R mutation." (PMID 32344833, 2020). "We will first describe and then use each method in turn to determine the whether SOS1 inhibition using BAY-293 could synergize with the EGFR-TKI osimertinib in EGFR-mutated lung adenocarcinoma cells." (PMID 32897190, 2020). "Understanding disease-related molecular mechanisms and profiles in lung adenocarcinoma affected differently depending on the type of EGFR gatekeeper mutation would be greatly useful in deciding treatment strategies that benefit the outcomes of individual patients." (PMID 32616892, 2020). "Moreover, consistent with the incidence of EGFR mutation in lung adenocarcinoma, the mutation rate was 46.7% in the Asian population and 15% in the white population." (PMID 33679868, 2020). "Here, we sought to investigate whether PD-L1 expression affects the efficacy of EGFR-TKIs and the clinical outcome in untreated metastatic EGFR-mutated lung adenocarcinoma patients." (PMID 32092879, 2020). "The results demonstrated that FGFR4 rs2011077 (odds ratio (OR) = 0.348, 95% confidence interval (CI) = 0.136–0.891, p = 0.024), and rs351855 (OR = 0.296, 95% CI = 0.116–0.751, p = 0.008) showed an inverse association with distant metastasis in wild-type EGFR lung adenocarcinoma." (PMID 32781755, 2020). "The L858R expression is a prevalent type of EGFR mutation that could harbor to the micropapillary component of lung adenocarcinoma and elevate the probability of tumor recurrence." (PMID 32365566, 2020). "But the correlation and mechanism of EGFR mutation status with the biological behavior and prognosis of lung adenocarcinoma remain unclear and controversial, and can be interfered by tumor stage, EGFR-TKI medication and other factors." (PMID 32127953, 2020). "More than half of lung adenocarcinoma patients in Japan harbor EGFR mutations, and resistance to EGFR tyrosine kinase inhibitors (TKIs) and relapse are associated with tumor clones harboring secondary-resistant mutations, which become more common during and after treatment." (PMID 31474751, 2020). "EGFR mutation detection was possible from 5% of lung adenocarcinoma cell lines." (PMID 32033355, 2020). "Also, the risk of lymph node metastasis of lung adenocarcinoma was lower likely with the CA9 SNP rs2071676 AG + GG in the EGFR wild type group (p = 0.005)." (PMID 32365566, 2020).
lung adenocarcinoma (continued). "FGFR4 SNPs may help in identifying patient subgroups at low-risk for tumor metastasis, among carriers of lung adenocarcinoma bearing wild-type EGFR." (PMID 32781755, 2020). "We analyzed the GSE31210 dataset to clarify whether the EGFR impact score can predict the prognosis of early-stage lung adenocarcinoma more accurately than EGFR structural mutations." (PMID 32277151, 2020). "The present study examined the relationship between four single-nucleotide polymorphisms (SNPs; rs2011077 T/C, rs351855 G/A, rs7708357 G/A, and rs1966265 A/G) of FGFR4 and the risk of lung adenocarcinoma with the epidermal growth factor receptor (EGFR) mutation status in a Taiwanese cohort." (PMID 32781755, 2020). "However, EGFR mutation rate are very high (51.8%) in Chinese lung adenocarcinoma population, and quite a few (56%) adenocarcinoma were ground glass opacity (GGO) which were not suitable for the study." (PMID 32043180, 2020). "Baseline demographics according to mutation types among EGFR positive lung adenocarcinoma subjects." (PMID 32053675, 2020). "Taking this into consideration, our study aimed to investigate the incidence and risk factors for LMC and to compare the clinical efficacies of various treatment modalities and clinical feasibility of the Ommaya reservoir, focusing on patients with lung adenocarcinoma harboring EGFR mutations." (PMID 31910497, 2020). "In addition to GSE31210, we analyzed GSE11969 data set which has early stage lung adenocarcinoma patients with EGFR mutation." (PMID 32277151, 2020). "We hypothesized that SOS1 could be an effective drug target to synergize with EGFR-TKI inhibition to treat EGFR-mutated lung adenocarcinoma." (PMID 32897190, 2020). "The main purpose of this study was to develop a radiomics nomogram based on 18F-FDG PET/CT radiomic features combined with clinicopathological factors to predict the survival outcomes of patients diagnosed with lung adenocarcinoma with an epidermal growth factor receptor (EGFR) mutation." (PMID 33262942, 2020). "We identified 1189 patients with lung adenocarcinoma harboring EGFR mutations." (PMID 31910497, 2020). "We investigated the risk factors for leptomeningeal carcinomatosis (LMC) and compared clinical efficacies of various treatment modalities including intrathecal (IT) chemotherapy in patients with lung adenocarcinoma harboring epidermal growth factor receptor (EGFR) mutations." (PMID 31910497, 2020). "Since our study only explores the Taiwanese group, it needs to further study whether the CD44 gene polymorphism is as a risk factor for the susceptibility of male lung adenocarcinoma, particularly those with wild-type EGFR, in other races." (PMID 32344833, 2020). "In EGFR-mutated lung adenocarcinoma, EGFR-TKIs show enhanced efficacy in spheroid cultures." (PMID 32897190, 2020). "Even though a growing number of studies have demonstrated that EGFR-stimulated cancer growth depends on SCD1 activity especially in lung adenocarcinoma, no investigations have been carried out to identify the relevance of SCD1 expression linked to EGFR-TKI resistance in lung adenocarcinoma." (PMID 30876460, 2019). "EGFR is a well-known gene that associated with lung adenocarcinoma." (PMID 31074380, 2019). "Our results indicated that histogram features may be helpful to diagnose and predict EGFR mutation status of metastatic bone lesions in patients with primary lung adenocarcinoma." (PMID 31174617, 2019). "Thus, not only the primary lung adenocarcinoma but also the bone metastases, range and skewness have a good judgment ability to EGFR mutation status." (PMID 31174617, 2019). "As per the analysis for concordance of EGFR activating mutations between primary lung adenocarcinomas and MC, on the basis of patients’ CSF samples, the results showed that, EGFR activating mutations in CSF samples were consistent with those in primary adenocarcinomas." (PMID 31856745, 2019).